MYD88 (MYD88 innate immune signal transduction adaptor)
Diseases named in the same sentence as MYD88 in open-access papers (continued):
Sharing a sentence is not in itself a finding about the gene and the disease.
infection (continued). "Integrated proteomic and in silico molecular docking analyses revealed favorable binding between punicalagin and several key innate immune proteins upregulated during infection, including Toll‐like receptor 2 (TLR2), its adaptor MyD88, and the cytokine macrophage migration inhibitory factor (MIF)." (PMID 41085014, 2026). "Supernatants harvested from either vector control or MyD88-transduced cells at d12 or 15 post-infection both suppressed the spread of HCMV, indicating that infection of wild-type cells can produce soluble factors that inhibit HCMV spread, albeit at a time point at which spread has already occurred." (PMID 40638072, 2025). "Supernatant harvested from either control- or MyD88-transduced cells on d3 post-infection failed to curb HCMV spread in the fresh monolayer." (PMID 40638072, 2025). "Although levels of MyD88 12 days after infection with UL88-STOP virus were reduced from d9 levels with either WT TB40/E or UL88-STOP HCMV, they were higher than those in d12 WT TB40/E infection and remained so until at least d15 post-infection." (PMID 40638072, 2025). "Among them, we wanted to analyze the expression of interferon α and β, IFITM3, ISG15, MyD88, and IRF1 in DF-1 and DSK cells upon MVA infection and verify whether their expression is affected when STING functionality is impaired." (PMID 40981440, 2025). "The UL88-dependent regulation of MyD88 is physiologically relevant, as infection is enhanced in the absence of MyD88, and spread from myeloid cells to fibroblasts is blunted in the absence of UL88." (PMID 40638072, 2025). "We found that Toll-1 knock-down in MyD88 cells rescued fly survival after 7 days of infection compared to non-infected controls, albeit not significantly when compared to infected RNAi controls." (PMID 39946503, 2025). "However, the infiltration of macrophages and dendritic cells to the infection site in DKK1(PKO) and MyD88(PKO) mice was significantly impaired on days 7 and 14 PI compared to infected BALB/c mice (& D)." (PMID 40502169, 2025). "The partial dependence of MLN ILC proliferation on MyD88 expression during infection contrasts to our previous study where we found no influence of this adaptor molecule on proliferation in peritoneal cavity ILC." (PMID 40299872, 2025). "Because DKK1 produced via the MyD88 activation signal promotes the migration of leukocytes to the infection site, we tested the hypothesis that the Th2 response in infected BALB/c mice may be mediated by DKK1 produced via a MyD88-dependent pathway." (PMID 40502169, 2025). "Indeed, of the ISGs examined, only ISG20 was upregulated in MRC-5 cells transduced with MyD88-expressing lentivirus relative to the MRC-5 cells transduced with the control lentivirus, and this ISG20 expression was increased upon infection with HCMV." (PMID 40638072, 2025). "At 24h post-infection, miR-1236-3p-m and si-TLR4 significantly reduced the expression of TLR4 and downregulated the phosphorylation level of p65, as well as the expression of TRAF6 and MyD88." (PMID 40502714, 2025). "Nonetheless, it is clear that the inhibition of HCMV spread in the presence of lentivirus-expressed MyD88 was dependent upon an extrinsic factor that was not produced in significant quantities until day 6 after infection." (PMID 40638072, 2025). "However, as HCMV spread in a culture following low MOI infection, UL88 mediated degradation of MyD88 and prevented heightened activation of surrounding cells mediated by an HCMV-triggered soluble factor." (PMID 40638072, 2025). "Significant upregulations could be observed for the genes TNFSF10 (3.8-fold change to WT infection), TNFRSF14 (3.2-fold) and MYD88 (1.9-fold)." (PMID 38400065, 2024).
infection (continued). "Pretreatment of IPEC-J2 cells (on insert membranes) followed by a 2 h infection with ETEC resulted in decreased mRNA levels for IL-1β, TLR5 (P < 0.001), and MyD88 (P < 0.05), but increased mRNA levels for IL-8, TNF-α (P < 0.001), and IL-6 (P < 0.01) compared to the control group of IPEC-J2 cells." (PMID 37875712, 2024). "We discovered that whereas most wild-type flies were able to overcome the infection, MyD88 or Toll mutant flies failed to prevent fungal dissemination and proliferation and ultimately succumbed to this challenge." (PMID 39239739, 2024). "We observed a knockdown efficiency of ~65% in mosquitoes knocked down for Myd88 compared to the GFP knockdown group (**p = 0.0044) and significantly higher infection and transmission rates (**p = 0.0056 and *p = 0.0353, respectively) in Myd88 knockdown group compared to the controls." (PMID 39466902, 2024). "Natural infection did not significantly kill T. marneffei conidia-injected MyD88 mutant flies faster than noninjected or PBS-injected controls, likely because of the barrier of the insect cuticle." (PMID 39239739, 2024). "Interestingly, seven weeks post infection, this pattern shifted, as BALB/c and C57BL/6 upregulated the expression of TLR2, TLR5, TLR8, TLR9, and MyD88 mRNA." (PMID 38896633, 2024). "Leendertse and colleagues firstly discovered that MyD88, at least in part through Toll-like receptor 2 (TLR2), is essential for the effective clearance of E. faecium during peritonitis by facilitating neutrophil recruitment to the infection site." (PMID 38951957, 2024). "However, CARD-9−/− and MyD88−/− mutant mice in theC57BL/6 background died after the challenge, suggesting the importance of both TLR and C-type lectin signaling in this route of infection." (PMID 38535182, 2024). "After infection with A. hydrophila, the transcriptional levels of TLR1, TLR2, caspase 8, MyD88, FADD, TOLLIP isoform 1 and TOLLIP isoform 2 were all significantly up-regulated in the kidney, indicating that bacterial infection induced the activation of TLR signaling pathway in the yellow catfish." (PMID 37056759, 2023). "In a recently established mouse model of infection with C. burnetii Nine Mile Phase II (NMII), we observed that efficient clearance of NMII from spleen, liver and lung was dependent on the TLR adapter protein MyD88." (PMID 36479617, 2023). "The MyD88/TRIF/NF-κB pathway, which is considered the primary regulatory downstream pathway of TLR4, mediates various inflammatory processes during LPS-induced infection." (PMID 37446388, 2023). "Overall, impairment of the TLR7/MyD88/IRAK-4 pathway prevents pDCs from producing sufficient type I IFN in response to SARS-CoV-2 in the respiratory tract, accounting for the patients’ vulnerability to infections with this virus." (PMID 36880831, 2023). "We observed, upon LdCen−/− infection, enhanced expression of TLR-9 receptor on DCs stimulated NF-κB signaling protein through MyD88-dependent mechanism to produce proinflammatory cytokines such as IL-12 and TNF, which have a protective function during Leishmania infection." (PMID 37111420, 2023). "However, in contrast to infection of the TLR2−/− and MYD88−/− macrophages, infection of p47phox−/− BMMs with the ∆tolC LVS still resulted in increased p38 phosphorylation at 30 and 60 min p.i.." (PMID 37404047, 2023). "It is also possible that other immune sensing pathways contribute to this response, as PMNs lacking MyD88 were still able to upregulate MitROS production in response to infection." (PMID 36374941, 2022). "However, we have recently shown that IL-18R/MyD88 signaling intrinsic to CD4+ T cells is critical for Th1 cell proliferation and resistance to apoptosis in response to infection with T. cruzi." (PMID 35670567, 2022). "Lack of TLR signaling via adaptor proteins MyD88 and TRIF in mice does not affect weight loss, morbidity or viral load during RSV primary infection." (PMID 35108347, 2022).
infection (continued). "Of note, the infection of mixed-bone marrow chimeras revealed that wild-type (WT) but not Myd88-/- cells transcribe the CD4CTL gene signature and that Il18ra-/- and Myd88-/- CD4+ T cells phenocopy each other." (PMID 35670567, 2022). "Interestingly, the expression of PRRs, MAPK signaling pathway genes (MyD88, AP-1, c-fos, Jun, JunD, MAX, and c-Myc), cytokines, chemokines, IFNs, and IFN-stimulated genes were increased after infection in resistant chickens." (PMID 34991196, 2022). "We next assessed the capacity of the infected MyD88 KO mice to transmit the infection to non-inoculated cage mates over 7 days of co-housing." (PMID 35395059, 2022). "Upon pathogen infection, TLR7 interacts with its corresponding ligands, and the intracellular Toll/interleukin-1 receptor homology (TIR) domain of activated TLR7 binds to and interacts with the carboxyl-terminus of MyD88." (PMID 35211622, 2022). "In summary, our experimental data show that, in the MyD88−/− SPF animals, a proper immune response outreaches the importance of the presence of the microbiome in preventing colonization and infection with Ye, and both YadA and the T3SS seem to play only a minor role in the colonization of the GIT." (PMID 35205164, 2022). "TLR4 uniquely signals through both the MyD88- and TRIF-dependent signaling cascades, but the respective contributions of these pathways in triggering trained immunity and host resistance to infection is unknown." (PMID 36439136, 2022). "Unlike S-LD, R-LD infection up-regulates miR-466i that targets MyD88 mRNA, leading to its down-regulation." (PMID 35925884, 2022). "As a result, we observed that MyD88 -/- monocytes failed to induce IL-1β after infection with L. corymbifera in contrast to WT monocytes." (PMID 36311802, 2022). "In contrast to these examples, GM-130, which is transcribed at a level that is slightly above the median for MyD88−/− BMDMs infected with L. pneumophila, showed no accumulation after infection." (PMID 36321832, 2022). "This suggests that the lower number of leukocytes at the site of infection is due to reduced recruitment of these cells in myd88-/- larvae rather than to an increased level of cell death." (PMID 33559740, 2021). "Nevertheless, a detailed picture on the emergence of MyD88-independent immunity, particularly in the intestine where infection initiates, is lacking." (PMID 34597344, 2021). "As predicted, infection of WT but not Myd88−/−/Trif−/− BMDM showed more than 50% reduction in Sirt3 by 24 h p.i.." (PMID 33531400, 2021). "Moreover, a reciprocal interplay between Neu1 and siglec-E differentially regulates MyD88- and TRIF-pathways through sialic acids on TLR4 as their common substrate during infection." (PMID 33763070, 2021). "We found that while IL-12 responses were lower in the absence of MyD88, an infection-induced response nonetheless persisted." (PMID 34597344, 2021). "Infection-induced IL-12 was lower in the absence of MyD88, but was still clearly above noninfected levels." (PMID 34597344, 2021). "have shown that the expression of TLR2, TLR4 and MyD88 did not change in bovine macrophages after 6 h of infection with M. bovis in relation to the non-infected control." (PMID 34335572, 2021). "However, we found that similar to Tnf transcription, TNF release upon Mtb infection was partially dependent upon MYD88 and TLR2 and very modestly increased upon infection with PDIM- or ESX-1-mutant Mtb." (PMID 34755600, 2021). "In addition, analysis of mRNA expression of adapter molecules involved in TLR signaling pathways demonstrated that infection with highly virulent T. cruzi strains induced inhibition in the expression of TRIF and MyD88 in the myocardium of infected animals." (PMID 34336720, 2021). "After infection with RV- SA11, the expression of TLR4, MyD88, and NF-κB mRNA and protein increased significantly, which could be abolished by SBP treatment." (PMID 33897431, 2021).
infection (continued). "Therefore, reduced Neu1, as well as enhanced siglec-E-TLR4 association through interaction with sialic acids, down-regulated both MyD88- and TRIF-pathways during infection." (PMID 33763070, 2021). "Similarly, the levels of MyD88, IκB-α, and NF-κB p65 crested at 12 h after LTA infection, followed by a continuous decline with an extended treated time of 24 h in RAW264.7 macrophages." (PMID 34136558, 2021). "It was found that the immune response of RV-infected mice lacking MyD88 was lower, which contributed to the infection and transmission of RV, and confirmed that MyD88-mediated TLR signaling pathway limited the infection and transmission of RV." (PMID 33897431, 2021). "Thus, in the context of infection, TLR and IL-1β signaling contributes to IgMFt production, but during immunization Myd88-mediated signaling appears dispensable." (PMID 34449811, 2021). "However, in response to infection, male mice exhibited higher expression levels of CXCL2 (KO, 1A3, and 6A2), SAMHD1 (1A0, 1A3), RSAD2, STAT1, and STAT3 (1A0), MYD88 and PSMB8 (1A3), BCL3, BCL10, CCRL2, IFITM2, RTP4, and ZFP36L1 (6A2), compared to females." (PMID 32670284, 2020). "This occupation of epithelial membranes by PDIM mediated subversion of TLR/Myd88 signaling at the site of infection, thus enabling mycobacteria to gain access to non-activated immune cells." (PMID 33226343, 2020). "Specifically, we characterized the effect of nicotine on MyD88 in association with TLR2 in presence and absence of infection." (PMID 33212859, 2020). "As previously reported, MyD88 KO mice did not control LVS infection; further, using this dose and route of infection, LVS control was only modestly dependent on TLR2 and TLR9." (PMID 32745117, 2020). "MyD88, TLR2, TLR3, and TLR4 peak at 48, 24, 12, and 36 h after infection." (PMID 31947624, 2020). "Although we and others have previously shown that TLR-2/MyD88 signaling can influence mucosal Foxp3+ cells, Treg specific role of MyD88 was not evaluated during an infection." (PMID 33240286, 2020). "While MyD88 KO mice ultimately do not survive infection, the days immediately preceding death are characterized by emergence of IFN-γ-producing Th1 effectors." (PMID 32413093, 2020). "Infection of WT mice with pathogenic, but not acutely cleared CHIKV, induced MyD88-dependent recruitment of monocytes and neutrophils to the dLN." (PMID 31999809, 2020). "In order to establish the role of Myd88 in the innate memory model, we infected Myd88-/- mice for 3 weeks and analyzed transcriptional priming (without secondary infection), as well as killing capacity and PML recruitment 5 days after re-challenge." (PMID 32639232, 2020). "However, in cells that were transfected with the SIAH1 siRNA or miR-424 mimic prior to infection, MyD88 expression was restored, suggesting that SIAH1 plays a role in the repression of MyD88 in DENV2 infected cells (lanes 3–4)." (PMID 32117091, 2020). "Collectively, these data confirm a nonredundant role of MyD88 in immunomodulatory function of Foxp3+ cells during the later phase of the infection in vivo." (PMID 33240286, 2020). "We performed initial experiments to establish the optimal dose for S. pneumoniae serotype 3 strain 1195 infection and the time required to mount an IIR, parameters that allowed us to study the myeloid cell subpopulations involved, as well as the role of TLR4 and MyD88 expression." (PMID 33042124, 2020). "Finally, to evaluate the role of MyD88 and TLR2 in controlling LVS infection and specifically IFN-γ production by DC, TLR2 KO and MyD88 KO mice were infected with LVS, DC and neutrophils from these mice were sorted, and DNA and RNA were analyzed." (PMID 32745117, 2020). "Consistent with the microarray, protein levels of GBP2 and GBP5 were reduced in the Ifnar1−/−, Irf9−/−, Irf1−/−, Trif−/−, and Irf3−/−Irf7−/− macrophages that undergo extensive cell-cell fusion during infection but not in Myd88−/−." (PMID 32150572, 2020).
infection (continued). "As a matter of fact, neutrophils recruited to the site of infection secrete IL12 and IFNγ, while monocytes contribute by secreting IL1β and TNFα, which in turn induce the secretion of IFNγ by neutrophils, NK cells and T cells in a MyD88-dependent way." (PMID 33178630, 2020). "Higher amounts of LVS and IFN-γ gene expression were quantified in cells from TLR2 KO mice which had higher bacterial burdens, while lack of MyD88 facilitated intracellular infection but little IFN-γ production." (PMID 32745117, 2020). "Therefore, we further investigated cytokine production by DC in MyD88 and selected TLR KO mice in response to LVS infection." (PMID 32745117, 2020). "Significant reduction of IFN-β was also observed in MLNs 5 days following oral infection with T. gondii cysts of mice lacking MyD88." (PMID 33324583, 2020). "However, IL-1 drives rapid vasodilation, and increases vascular permeability via a MYD88-ARNO-ARF6 pathway within 15 mins, enabling rapid extravasation of complement and leucocytes to sites of injury and/or infection." (PMID 30926232, 2019). "In the murine model of infection, robust IL-12 and IFN-γ production have been largely attributed to T. gondii profilin recognition by the TLR11 and TLR12 heterodimer complex, resulting in Myd88-dependent IL-12 production." (PMID 31194844, 2019). "It is not clear how MyD88 induces activation of mTORC1 in macrophages following infection with virulent IOE." (PMID 31134081, 2019). "While wild-type mice essentially cleared NMII on day 27 after intratracheal infection, it was still readily detectable on day 42 in multiple organs in the absence of MyD88." (PMID 30800124, 2019). "Production of IL-1β was almost completely abrogated in the absence of MyD88 following infection with both S. suis strains (p < 0.01)." (PMID 31262357, 2019). "Western blot experiment results showed that, at the 3rd and 7th days after infection, protein expression levels of TLR4, TLR7, MyD88 and NF-κB p65 in the murine lung tissues of the control infected group were significantly higher than those in the control uninfected group (all P < 0.01)." (PMID 31551774, 2019). "Myd88-deficient mice infected with CHIKV, like TLR3−/− mice, did not succumb to infection but developed significant viral dissemination." (PMID 30909385, 2019). "Robust IL-12 production during mouse infection is largely attributed to direct recognition of T. gondii profilin by TLR11 which forms a heterodimer complex with TLR12 and leads to the activation of Myd88-dependent signaling pathways." (PMID 31194844, 2019). "The calculated rates at 2 and 4 h showed, that strain ISS3319 is able to proliferate within the first 4 h post-infection in BMM and MyD88−/-, while the survival rates of other C. diphtheriae strains, except the toxigenic strain DSM43989, remained at least constant." (PMID 31057086, 2019). "A moderate but significant decrease in body weight was observed in Myd88+/− mice on day 2 after infection, but not in Myd88−/− mice." (PMID 30800124, 2019). "Analysis of the parasite burden revealed that while TLR11 was the primary mediator of parasite control at the site of infection, Casp1/11 plays an important role in cooperation with TLR11 in providing systemic Myd88-dependent immunity towards this intracellular pathogen." (PMID 31194844, 2019). "The induction of cytokines (IL6 and TNFα), chemokines (CCL2 and CXCL10), and IFN-I genes in primary C57BL/6 astrocytes following a TMEV-BeAn infection can be mediated by TLR3 but not TLR7 or other MyD88-mediated pathways." (PMID 30669615, 2019). "In contrast to wild-type BMDMs, infection of MyD88−/− BMDMs with PGL-expressing rBCGs did not alter their relative production of NO." (PMID 29403489, 2018). "Of note, MYD88, a downstream effector for TLR2 activation of transcription, is also a strong hit in our dependency factor screening suggesting that it is the downstream signaling functions of TLR2 that enhance infection." (PMID 30520725, 2018).